PINK1 (PTEN induced kinase 1)
Diseases named in the same sentence as PINK1 in open-access papers (continued):
Sharing a sentence is not in itself a finding about the gene and the disease.
tumor (continued). "One hundred and fourteen matched human NSCLC tumor/normal pairs were examined by real-time q-PCR analysis for expression of PARK1/4 (SCNA), PARK2 (Parkin), PARK5 (UCHL1), PARK6 (PINK1), PARK7 (DJ-1), PARK8 (LRRK2), PARK9 (ATP13A2), PARK15 (FBXO7), and GBA mRNA." (PMID 26245297, 2015). "Moreover, PINK1 and PI3K may influence the tumor microenvironment, particularly through their interactions with immune cells and their role in controlling the inflammatory response." (PMID 40243539, 2025). "Therefore, the PINK1/PARK2 signaling pathway may regulate the glucose metabolism of tumors by regulating mitochondrial function, thereby regulating tumor proliferation and metastasis and mediating tumor prognosis." (PMID 37833780, 2023). "Furthermore, serial section analysis of IF showed that the expression levels of PINK1 and p-Drp1Ser616 were upregulated, and the colocalization of PINK1 and p-Drp1Ser616 was increased in HCC tumor (T) tissues compared to the corresponding peritumor (P) tissues." (PMID 35159089, 2022). "In addition, although our work does not place PINK1 in a Ras-dependent transformation pathway, separate projects addressing such a possibility with additional transformed tumor models may be interesting." (PMID 35600352, 2022). "Previous study found impaired PINK1 and PRKN expression could promote the degradation of SLC25A37 and SLC25A28 and increase the mitochondrial iron accumulation, which lead to AIM2-mediated HMGB1 release that further induced expression of CD274/PD-L1 in tumor cells." (PMID 36612054, 2022). "Mitochondria-eating protein (MIEAP) is a key molecule involved in non-canonical mitophagy which is independent of the PTEN-induced kinase 1 (PINK1)/Parkin pathway, and it is considered as a tumor suppressor." (PMID 40069775, 2025). "Moreover, a positive relationship was observed between PINK1 levels and serum expression of CA125 and ascites volume, but not tumor diameter." (PMID 37940999, 2023).
neurodegenerative disease (99 papers, 2007 to 2026). A disorder of the central nervous system characterized by gradual and progressive loss of neural tissue and neurologic function. "Non-hypoxic induction of mitophagy can be modulated by one of the three classical pathways, the PINK1/Parkin pathway, which plays causative roles in neurodegenerative disease." (PMID 40585980, 2025). "PINK1/Parkin-dependent mitophagy is an extensively studied form of mitophagy and has been implicated in the pathogenesis of neurodegenerative diseases." (PMID 37958902, 2023). "In particular, PINK1 has been associated with the onset and progression of many neurodegenerative diseases including AD, and PINK1 downregulation leads to mitochondrial dysfunction, increase oxidative stress, and neuronal dysfunction." (PMID 36950017, 2023). "Studies have reported that mitochondrial dysfunction and bioenergy deficiency in many neurodegenerative diseases can be alleviated by stimulating PINK1/Parkin-mediated mitophagy." (PMID 37958902, 2023). "PINK1/Parkin-mediated mitophagy is a well-known selective autophagy pathway to remove dysfunctional mitochondria and is associated with diverse neurodegenerative diseases." (PMID 37745295, 2023). "Since its discovery as a causative gene in PD, PINK1 has been studied in the context of several neurodegenerative diseases." (PMID 35203326, 2022). "Small molecules identified through screening for the ability to induce mitochondrial fragmentation and autophagosome formation ameliorate proteostasis defects associated with neurodegenerative diseases in Caenorhabditis elegans in a Pink1-dependent manner." (PMID 36407069, 2022). "Defects in mitochondrial homeostasis are a key part of the aetiology of neurodegenerative diseases; for example, mutations in PINK1 and Parkin are associated with early onset familial Parkinson’s disease." (PMID 34152608, 2021). "Mitochondrial dysfunction has been linked to the pathogenesis of neurodegenerative diseases including PD, with mutations identified in mitochondrial-associated proteins such as PINK1 and parkin causing familial PD." (PMID 31931835, 2020). "This idea is supported by studies showing that some neurodegenerative disease models, such as reduced frataxin expression or PINK1 mutation, show reduction of both mitochondrial transport and membrane potential." (PMID 28542430, 2017). "PINK1/Parkin-mediated mitophagy is a well-known form of selective autophagy that targets damaged or unwanted mitochondria for lysosomal degradation and is associated with multiple human diseases, especially neurodegenerative diseases." (PMID 38933121, 2022). "The c.892C>T variant has been identified as causing PINK1/Parkin pathway inhibition and mitochondrial injuries in neurons, leading to apoptosis and autophagy resistance, potentially triggering neuronal cell death and the onset of developmental and neurodegenerative diseases." (PMID 39421062, 2024). "Many neurodegenerative diseases are characterized by the accumulation of neurotoxic protein aggregates resulting from mutations in the genes encoding for proteins that trigger mitophagy: PTEN-induced kinase 1 (PINK1), parkin, and protein deglycase DJ-1, among others." (PMID 34638589, 2021). "The central role of mitophagy in neurodegenerative diseases is primarily driven by the PINK1-Parkin pathway, which has emerged as the key framework in the field, particularly in PD." (PMID 41426598, 2025). "The involvement of PINK1/Parkin signaling is particularly noted in the context of neurodegenerative diseases." (PMID 41008559, 2025). "MT modulates PTEN-induced putative kinase 1 (PINK1) expression via the MT2/Akt/NF-κB pathway to inhibit neuronal apoptosis in neurodegenerative diseases." (PMID 41422263, 2025). "The link between PINK1, Parkin, and mitophagy has been studied in degenerative diseases, cardiovascular diseases, and tumors." (PMID 39290494, 2024).
neurodegenerative disease (continued). "The Parkin/PINK1 mediated mitophagy has been shown to have a protective effect for patients with neurodegenerative disease." (PMID 38632223, 2024). "As a ubiquitin-dependent pathway, PTEN-induced kinase 1 (PINK1)–Parkin-mediated mitophagy was the first identified and most studied in neurodegenerative disease." (PMID 36831455, 2023). "We described an earlier disease onset in GRN/C9orf72 pedigrees in subjects carrying the p.Asn521Thr variant in PTEN-induced kinase 1 (PINK1), thus highlighting a gene already known to be strongly involved in various neurodegenerative diseases." (PMID 36361641, 2022). "OMA1 suppression, however, cancels PINK1 import into the mitochondria and activates mitophagy, and therefore is considered as a potential therapy to stimulate mitophagy for neurodegenerative diseases." (PMID 36088658, 2022). "We described an earlier disease onset in GRN/C9orf72 pedigrees in subjects carrying the p.Asn521Thr variant (rs1043424) in PTEN-induced kinase 1 (PINK1), a gene that is already known to be involved in neurodegenerative diseases." (PMID 36361641, 2022). "This review summarizes the mechanisms of PINK1/Parkin dependent mitophagy and describes how mitophagy is altered in multiple neurodegenerative diseases." (PMID 36339819, 2022). "Efforts to target PINK1 with candidate therapeutics for neurodegenerative diseases have so far focused on its kinase activity." (PMID 35203326, 2022). "Through these varied roles PINK1 directly influences functions central to cell dysfunction in neurodegenerative disease." (PMID 34897410, 2021). "Research into these alternative pathways presents a promising candidate for the development of therapeutics targeting neurodegenerative diseases featuring defective PINK1/Parkin mitophagy." (PMID 34897410, 2021). "An insightful comparative omics profiling study analyzed, among other measures, the brain transcriptomic profile of models for different neurodegenerative diseases, including one PD model (Pink-1 knockout mice)." (PMID 32997293, 2021). "PINK1 is a broad-acting kinase that regulates biochemical pathways key to dysfunction in neurodegenerative disease." (PMID 34897410, 2021). "Since deregulation of park and/or Pink1 expression relates to human degenerative diseases, we focused our studies on park, Pink1 KD-mediated functional outputs." (PMID 34218254, 2021). "While we focus here on the PINK1/Parkin pathway, given its genetic links to neurodegenerative diseases like PD and ALS, it is likely that additional and potentially compensatory pathways are actively contributing to mitochondrial quality control in neurons." (PMID 31934852, 2020). "Mitochondrial autophagy plays an important role in the self‐maintenance of the nervous system, but only the role of PINK1/Parkin pathway in the regulation of neurodegenerative diseases has been well specified so far, and some results are still controversial." (PMID 31050206, 2019). "Our work has established the neuronal protective role of Pink1 against oxidative stress and affords rationale for developing new strategy to the therapy of neurodegenerative diseases." (PMID 25608948, 2015). "Our findings have established the neuronal protective role of Pink1 against oxidative stress and afford rationale for developing new strategy to the therapy of neurodegenerative diseases." (PMID 25608948, 2015). "The PARL cleaves human PINK1 within its conserved membrane anchor, suggesting implication in neurodegenerative disease." (PMID 23533695, 2013). "It has been shown that factors contributing to neurodegenerative diseases, such as PINK1 and Parkin, affect both mitochondrial fusion and fission depending on the cell type and culture conditions." (PMID 23284813, 2012). "The PINK1/Parkin autophagy pathway is known for its decisive role in neurodegenerative diseases." (PMID 39761309, 2025).
neurodegenerative disease (continued). "However, direct evidence for a role of PINK1/Parkin mediated mitophagy in modulating neurodegenerative disease pathogenesis in animal models is limited." (PMID 38394123, 2024). "Overall, our data are consistent with the PINK1/Parkin pathway of mitophagy helping to slow the progression of a neurodegenerative disease in vivo by maintaining healthy, functional mitochondria and limiting the damage induced by ROS generated by dysfunctional mitochondria." (PMID 38394123, 2024). "PINK1/Parkin regulates the initiation of mitophagy, which is crucial for mitochondrial quality control, potential interventions centered around their regulation of mitophagy are thought to offer new strategies for the treatment of neurodegenerative diseases." (PMID 38575939, 2024). "Our findings may open new avenues for the design of novel therapeutic approaches targeting KAT8 for neurodegenerative diseases such as PD, in which defective PINK1-mitophagy plays a central role." (PMID 38777823, 2024). "In conclusion, our study suggests that gefitinib promotes PINK1/Parkin-mediated mitophagy via OPTN and may be beneficial for the treatment of neurodegenerative diseases that are associated with defective mitophagy." (PMID 38933121, 2022). "Additionally, studies of other neurodegenerative disease models confirmed that PINK1, parkin gene interventions also affect pathological changes caused by those diseases." (PMID 35184140, 2022). "We characterized a new anti-apoptotic function of PINK1 that could provide options for treatment in proliferative or neurodegenerative diseases." (PMID 35203326, 2022). "Here, we review the multiple roles played by PINK1, including the PINK1/parkin signalling pathway and briefly outline alternative PINK1/Parkin-independent mechanisms of mitophagy that may be leveraged as therapeutics for neurodegenerative disease." (PMID 34897410, 2021). "Various studies have indicated that the activation of PINK1 could be a useful strategy in treating neurodegenerative diseases, such as PD." (PMID 29226533, 2018). "Given the prevalence of dendritic pathology in neurodegenerative diseases, further study of these processes may offer important insights regarding how PINK1 and VCP function to prevent neurodegeneration." (PMID 30783609, 2018). "In addition, the results demonstrated that maintaining mitochondrial homeostasis via PINK1/Parkin-dependent mitochondrial quality control can potentially alleviate cell death in a wide range of neurodegenerative diseases." (PMID 27054334, 2016). "A study of mouse models of neurodegenerative diseases revealed that PINK1 knockout, instead of Parkin knockout, results in a continuous neurodegenerative disease—indicating that other PINK1-dependent phosphorylation sites might compensate for the role of Parkin in mitophagy." (PMID 35203359, 2022). "Importantly, we found that treatment with two compounds, which we named PS83 and PS106 (more commonly known as sertraline) reduced neurodegenerative disease phenotypes, including delaying paralysis in a C. elegans β-amyloid aggregation model in a PINK-1-dependent manner." (PMID 34489512, 2021). "Thus, the redox system in the IMS is involved in PINK1 accumulation and damaged mitochondrial clearance, which may play roles in mitochondrial dysfunction‐related neurodegenerative diseases." (PMID 32779864, 2020). "In neurodegenerative disease states, however, processes that serve to suppress retraction and elimination of dendritic branches and spines are differentially impaired, and the potential role of the PINK1-VCP-PKA-p47 signaling cassette in these contexts remain to be determined." (PMID 30783609, 2018). "Whether PINK1 levels are enhanced or reduced, strategies to promote selective mitophagy and mitochondrial biogenesis may prove to be effective for multiple forms of neurodegenerative disease." (PMID 23533695, 2013).
neurodegenerative disease (continued). "Understanding this novel regulatory mechanism provides a deeper insight into the pathological function of PINK1 and SMAD3 in the pathogenesis of neurodegenerative diseases such as PD." (PMID 40064862, 2025). "In the MM1 subtype, we found variants in genes involved in a heterogeneous group of molecular processes and neurodegenerative diseases, while in the VV2, we found an over-representation of genes involved in PD, such as HTRA2, PINK1, and PRKN." (PMID 36517866, 2022). "However, our results show that there is a substantial increase in the levels of P-parkin in IL-1β-treated neurons (p < 0.001), suggesting that a kinase other than PINK1 can phosphorylate parkin and may do so in conditions, such as those in neurodegenerative diseases, where IL-1β levels are elevated." (PMID 31882005, 2019). "Thus, we hypothesized that SIAH3 can affect the PINK1/Parkin mitophagy by inhibiting the accumulation of PINK1 in the damaged mitochondria, subsequently leading to mitochondrial dysfunction involved in the pathology and pathogenesis of neurodegenerative diseases." (PMID 31711042, 2019). "This review describes the dysfunctions of mitochondria in aging and neurodegenerative diseases, and the signaling pathways leading to mitochondrial biogenesis (including PGC‐1 family proteins, SIRT1, AMPK) and mitophagy (parkin‐Pink1 pathway)." (PMID 30889315, 2019). "In addition, PTEN-induced kinase 1 (PINK1) and Parkin RBR E3 ubiquitin-protein ligase (Parkin) are markers of dysfunctional mitochondria destined for mitophagy in neurodegenerative diseases such as PD." (PMID 37239873, 2023). "Therefore, there is an increasing interest in stimulating mitophagy (PINK1–PARKIN-dependent and -independent) to treat HD and other neurodegenerative diseases." (PMID 33922020, 2021). "Defective dysfunctional mitochondrial removal was revealed in the progress of neurodegenerative diseases with the absence of functional parkin and PINK1." (PMID 29201272, 2017). "Thus, the transmission of mitochondrial damage to the nucleus, where it manifests as DNA double-strand breaks via the PINK1–Parkin–BRCA1 axis, may be relevant not only in the field of oncology, but also in the study of neurodegenerative diseases." (PMID 33888730, 2021). "The observations that PINK1 and parkin affect mitochondrial dynamics has expanded the interest beyond the electron transport chain to include mitochondrial fission, fusion, and movement, not just in PD but also in other neurodegenerative diseases such as AD, HD and ALS." (PMID 38504290, 2024).